ZNF823 (zinc finger protein 823)
Description:
May be involved in transcriptional regulation.
Synonyms: HSZFP36
Tractability: PROTAC: ubiquitination databases record sites on it.
Gene: Protein-coding gene on chromosome 19 (11,721,264 to 11,739,009, reverse strand). Ensembl gene ENSG00000197933.
Subcellular location: Nucleus
Gene Ontology:
Molecular function: DNA-binding transcription factor activity, RNA polymerase II-specific; RNA polymerase II transcription regulatory region sequence-specific DNA binding
Biological process: regulation of transcription by RNA polymerase II; regulation of DNA-templated transcription
Cellular component: nucleus
Genetic constraint (gnomAD): Loss-of-function variants: 4 observed, 10.49 expected, observed/expected ratio (o/e) 0.38, 90% interval 0.19 to 0.87. The upper end of that interval is the gene's LOEUF score, 0.87, which puts it in group 3 of 6, group 1 being the genes least tolerant of losing a copy. Missense variants: 581 observed, 769.34 expected, observed/expected ratio (o/e) 0.76, 90% interval 0.7 to 0.81. Synonymous variants: 234 observed, 262.52 expected, observed/expected ratio (o/e) 0.89, 90% interval 0.8 to 0.99.
Homologues: Orthologues: chimpanzee ZNF823 (99% identical), macaque ZNF823 (97% identical), rat Zfp617 (33% identical), mouse Zfp961 (32% identical). Paralogues in human: ZNF443 (77% identical), ZNF799 (77% identical), ZNF44 (75% identical), ZNF442 (74% identical), ZNF441 (62% identical), ZNF709 (57% identical), ZNF700 (57% identical), ZNF433 (55% identical), ZNF563 (55% identical), ZNF14 (52% identical), ZNF791 (51% identical), ZNF878 (46% identical), and 3 more.
Diseases named in the same sentence as ZNF823 in open-access papers:
ZNF823 is named in the same sentence as 12 diseases in open-access papers, as found by Europe PMC text mining. Sharing a sentence is not in itself a finding about the gene and the disease. The quoted sentences say what the papers report.
Down syndrome (1 paper, 2020). "Signatures of ZNF823 has also been reported in Down syndrome and perturbation of immunological pathways upon vaccination." (PMID 33343624, 2020).
gastric cancer (1 paper, 2020). A primary or metastatic malignant neoplasm involving the stomach. "The functions of ZNF823, ZFP69B, SP6, KYNU, KIF21B, and TTF2 have not been reported in gastric cancer." (PMID 32848739, 2020).
ZNF823 also shares sentences with these, for which no sentence is quoted: schizophrenia (3 papers); agoraphobia (1); anxiety disorder (1); autism (1); autism spectrum disorder (1); carcinoma (1); generalized anxiety disorder (1); social anxiety disorder (1); tuberculosis (1); tumor (1).